IL15 (interleukin 15)
Diseases named in the same sentence as IL15 in open-access papers (continued):
Sharing a sentence is not in itself a finding about the gene and the disease.
myeloid leukemia (6 papers, 2017 to 2023). A clonal proliferation of myeloid cells and their precursors in the bone marrow, peripheral blood, and spleen. "K562mb15-41BBL is a myeloid leukemia cell line that is genetically modified to express membrane-bound interleukin-15 and 41BB ligands in order to specifically activate NK cells but not T lymphocytes." (PMID 38003255, 2023). "In fact, myeloid leukemia mouse model studies showed that sorafenib increases IL-15 production in FLT-ITD-positive leukemic cells which synergizes with the allogeneic CD8+ T-cell response." (PMID 35943684, 2022). "IL-12, IL-15, and IL-18 enable NK cells to further mature, and induce memory-like functions to strengthen their cytotoxicity toward myeloid leukemia." (PMID 28915651, 2017).
nephropathies (6 papers, 2016 to 2024). "TGF-β1-induced apoptosis and fibrosis in experimental chronic murine kidney diseases are concomitantly associated with an intrarenal decreased expression of the IL-15 survival factor." (PMID 31360169, 2019). "Interestingly, decrease in intrarenal IL-15 was closely linked to changes in IL-15Rα in several murine experimental nephropathies." (PMID 31360169, 2019). "Boxplot performed on IL-15 transcript quantification showed a downregulation in several nephropathies as compared to the control donors and this global tendency was found confirmed by Student's t-test (p value = 0.0038)." (PMID 31360169, 2019). "Since intrarenal IL-15 is strongly decreased in several experimental murine nephropathies and human renal dysfunction, we investigated the IL-15 expression profile of the renal medulla of lithium-induced renal fibrosis by bioinformatics based on Gene Expression Omnibus (GEO) datasets." (PMID 35252184, 2022). "Overall, our study demonstrates that IL-15 may be an important player in renal fibrosis and may be considered as a novel therapeutic agent in renal disease as a repurposing drug." (PMID 34769128, 2021). "Since intrarenal IL-15 is strongly decreased in several experimental murine nephropathies compromising renal function, we have first investigated the IL-15 expression profile for kidney biopsies of transplant patients and of human nephropathies by bioinformatics based on microarray datasets." (PMID 31360169, 2019). "In addition, in several murine experimental nephropathies there is a sharp and rapid decrease of intrarenal IL-15, which is detrimental to renal cell survival and kidney function during pathological stress." (PMID 31360169, 2019). "Interestingly, we found a significant IL-15 decreased expression at transcriptional level in human nephropathies by bioinformatics based on microarray datasets." (PMID 31360169, 2019). "It is tempting to suggest that intrarenal mbIL-15 is a natural inhibitor of intrarenal TGF-β1 and that therapeutic strategy to restore or increase IL-15 level in injured kidney could be beneficial in some human nephropathies such as diabetic nephropathy." (PMID 31360169, 2019). "Exogenous IL-15 treatment could be beneficial in some human nephropathies such as diabetic nephropathy." (PMID 31360169, 2019). "To confirm this hypothesis, we first investigated IL-15 expression in various human nephropathies." (PMID 31360169, 2019). "Thus, it is possible that, in some human nephropathies, an unbalanced production of intrarenal IL-15 and TGF-β1 could render epithelial cells more prone to fibrogenic stimuli." (PMID 31360169, 2019).
osteoporosis (6 papers, 2023 to 2025). A condition of reduced bone mass, with decreased cortical thickness and a decrease in the number and size of the trabeculae of cancellous bone (but normal chemical composition), resulting in increased fracture incidence. "IL‐15 is a key factor in the prevention and treatment of muscle atrophy and degeneration as well as osteoporosis, infection, and other chronic diseases; however, upstream regulators, downstream effectors and detailed signalling pathways have not been comprehensively characterized." (PMID 39601091, 2024). "By inhibition of the Wnt pathway, these proteins along with several other cytokines, such as IL‐15, interferon gamma, IL‐17 MCP‐4 (monocyte chemoattractant protein), and TNF‐α blunt the bone formation there by leading to osteoporosis and its sequelae." (PMID 36911094, 2023).
renal failure (6 papers, 2019 to 2023). "In this context, an increase in the expression of TGF-β observed in multiple nephropathies, which is associated with a decrease in the expression of IL-15, may be critical in promoting fibrogenesis and renal failure." (PMID 34769128, 2021). "We also identified several organ-failure-specific immunological markers, including those for respiratory (IL-18, IL-15, Gal-9) or kidney failure (CD28, VEGF)." (PMID 34177897, 2021). "The only advent of kidney failure, liver failure, and need for pressors was associated with elevation of specific markers (CCL4, CD40, CXCL5, and IL-15), but our findings’ interpretation needs more broad context." (PMID 34177897, 2021). "In this context, an increase of TGF-β production associated with a decreased activity of endogenous antifibrotic factors such as IL-15 may explain, at least in part, fibrosis development and renal failure in multiple nephropathies." (PMID 31360169, 2019).
T-cell leukemia (6 papers, 2020 to 2024). A malignant disease of the T-lymphocytes in the bone marrow, thymus, and/or blood. "On the other hand, we reported the development of fatal T cell leukemia arising from developing thymocytes in IL-15-deficient NOD.Scid mice." (PMID 36765626, 2023). "First evidence of the leukemogenic effects of IL-15 was described in 1994 in HTLV1-associated human T cell leukemia, where IL-15 levels were highly increased and anti-CD122 monoclonal antibody treatment reduced leukemic cell growth." (PMID 33445786, 2021).
T-cell lymphoma (6 papers, 2020 to 2023). "IL-15 sustains chronic inflammation, autoimmunity, and uncontrolled T-cell proliferation, leading to T-cell lymphoma development." (PMID 37153603, 2023). "modified a CD5-IL-15/IL15sushi CAR which secretes an IL-15/IL-15 complex, to explore its clinical effectiveness against one refractory T-cell lymphoma patient with CNS infiltration." (PMID 36523990, 2022). "EATL is the other epitheliotropic T-cell lymphoma in the GI tract, a subset of which arises from the expansion and reprograming of intracytoplasmic CD3+ innate lymphoid cells, driven by IL15 and mutations of the JAK-STAT pathway." (PMID 35626087, 2022).
triple-negative breast carcinoma (6 papers, 2015 to 2023). An invasive breast carcinoma which is negative for expression of estrogen receptor (ER), progesterone receptor (PR), and human epidermal growth factor receptor 2 (HER2). "Here, we found that when human NK cells were exposed to a similar cytokine environment to that found in IL-15 overexpressed MT tumors, they were highly capable of killing a triple negative breast cancer cell line." (PMID 25879689, 2015).
bladder tumors (5 papers, 2012 to 2024). "Adenoviral vectors encoding IL-15 were also found to be able to abolish tumorigenicity of murine bladder tumor MB4941." (PMID 27273619, 2016). "In addition, the importance and role of cytokines, including IL-2, IL-12, IFN-gamma, IL-6, and IL-15, in inhibiting the incidence and growth of bladder tumors has been established." (PMID 22962576, 2012).
chronic myelogenous leukemia (5 papers, 2022 to 2025). "Also, feeder cells, such as the chronic myeloid leukemia-derived cell line (K562), in combination with cytokines or expression of membrane-bound IL-15, IL-21, or 4-1BB are often used to enhance NK cell proliferation." (PMID 36762286, 2023).
cognitive decline (5 papers, 2020 to 2024). "Finally, combinations of four molecules improved prediction of both AD (protein 14-3-3 zeta/delta, clusterin, interleukin-15, and transgelin-2) and cognitive decline (protein 14-3-3 zeta/delta, clusterin, cholesteryl ester 27:1 16:0 and monocyte chemoattractant protein-1)." (PMID 33794997, 2021). "For example, the blood-borne SASP proteins IL-15 and chemokine (C-C motif) ligand 3 (CCL3) are correlated with chronological age and cognitive decline." (PMID 32848716, 2020).
dementia (5 papers, 2015 to 2025). Loss of intellectual abilities interfering with an individual's social and occupational functions. "Due to elevated levels observed in dementia patients 58, IL15 has previously been investigated as a biomarker for AD and frontotemporal dementia (FTD)." (PMID 38343831, 2024). "CSF levels of YKL-40, ICAM-1, VCAM-1, IL-15, and Flt-1 were increased during the preclinical, prodromal, and dementia stages of AD." (PMID 30054439, 2018). "IL-15’s effects on cognitive performance via d should protect against dementia, even as its effects via g’ impair cognitive performance." (PMID 25710473, 2015). "In the present analysis, also using the TARCC dataset, we set out to explore the possibility that serum levels of IL-15 can assist in diagnosis of dementia." (PMID 25710473, 2015). "In the present study, using a large cohort of well-characterized patients, we show increased levels of ICAM-1, VCAM-1, IL-15, and Flt-1in AD at the preclinical, prodromal, and dementia stage, indicating that neuroinflammatory pathways are activated early in the disease course." (PMID 30054439, 2018). "It is the largest study to date of IL-15’s association with cognitive performance in humans and we have associated IL-15 with a latent dementia phenotype rather than with categorical diagnoses." (PMID 25710473, 2015).
fungal infections (5 papers, 2019 to 2025). "IL-15 plays a role in innate immunity against fungal infections by boosting the antifungal activity of polymorphonuclear or monocyte cells; it also recently has been found to play a part in NK cell activation." (PMID 38774871, 2024). "Using IL-15 deficient mice, several studies have established the requirement of IL-15 to efficiently control bacterial, viral and fungal infections presumably through its functions on lymphoid subsets, which require trans-presentation." (PMID 34956227, 2021). "Other cytokines also related to fungal infections are IL-8, IL-10, and IL-15, as well as the already mentioned IL-17." (PMID 31484389, 2019). "The results of studies indicate that IL15, FLT3L, CXCL10, and IL1B, which demonstrated the most promising outcomes among the estimates, are actually associated with numerous viral, bacterial, parasitic, and fungal infections." (PMID 40650062, 2025). "The antifungal cytokines—Type1 (IL-7 and IL-15), Th17 (IL-7), and proinflammatory (IL-11)—were all significantly enhanced in CBM patients, presumably as a compensatory response to the long-term fungal infection." (PMID 35252030, 2022).
head and neck squamous cell carcinoma (5 papers, 2018 to 2022). A squamous cell carcinoma that arises from any of the following anatomic sites: lip and oral cavity, nasal cavity, paranasal sinuses, pharynx, larynx, and salivary glands. "IL-15 is an important cytokine for NK cell homeostasis and activation, and the presence of IL-15 within the TME was associated with NK cells with high anti-tumor function in head and neck squamous cell carcinoma (HNSCC)." (PMID 35720306, 2022). "We generated a library of helper-dependent Ads expressing various cytokines (IL2, IL7, IL-12p70, IL15, and IL21) and screened them for their ability to enhance HER2.CAR-T mediated killing of head-and-neck squamous cell carcinoma (HNSCC) targets." (PMID 30298067, 2018). "The differential fates of g1 ILCs and a potential role of IL-15 also became apparent in the scRNA-Seq analysis of Lin- CD56+ and/or CD127+ cells from tumor and PB samples derived from patients with head and neck squamous cell carcinoma (HNSCC)." (PMID 36372017, 2022).
Hyperglycemia (5 papers, 2013 to 2025). An increased concentration of glucose in the blood. "In this study, Ephx2, Stc2, Cep19, Il15 and Fbxw7 genes were found to be associated with impaired glucose tolerance and hyperglycemia." (PMID 32095365, 2020). "Thus, the significantly downregulated Stc2, Il15, and Fbxw7 might associate with hyperglycemia and impaired glucose tolerance in GK rats at 3 and 4 weeks of age." (PMID 32095365, 2020). "Notably, anti-CD132 or anti-IL-15 protected NOD mice from the cyclophosphamide-accelerated onset of hyperglycemia as a precaution." (PMID 40957221, 2025). "In the presence of IL-15, NK cell degranulation was fully restored, indicating that IL-15 retains its capacity to enhance NK cell activity, even when these cells have been exposed to sustained hyperglycemia." (PMID 23638076, 2013).
Hypertension (5 papers, 2007 to 2025). The presence of chronic increased pressure in the systemic arterial system. "One previous study evaluated the effects of IL-15 on cardiovascular complication in patients with hypertension." (PMID 17784951, 2007). "Inflammation plays an important role in regulating BP and hypertension, so IL‐15 or IL‐15Rα could also have effects on BP and hypertension." (PMID 34586716, 2021).
idiopathic inflammatory myopathies (5 papers, 2015 to 2025). "IL-6, IL-15, and IL-18 have been noted to be elevated systemically in patients with idiopathic inflammatory myopathies (IIM)." (PMID 41488665, 2025). "Muscle-resident CD8+ T cells in idiopathic inflammatory myopathies are predominantly CD28 negative (CD8+CD28null) and IL-15 has been implicated in their generation." (PMID 26646698, 2015). "IL-15 and NKG2D as well as their cognate ligands might be important in stabilizing the immunological synapse between CD8+ T cells and MHC class I expressing muscle cells in idiopathic inflammatory myopathies." (PMID 26646698, 2015).
leprosy (5 papers, 2018 to 2025). Leprosy is a chronic infectious disease affecting primarily the skin and peripheral nervous system. "To model the MΦ subtypes in leprosy lesions, we studied MΦ subsets derived in vitro with IL-15- vs. IL-10-treated monocytes yielding M1-like vs. M2-like MΦ, respectively." (PMID 30300363, 2018). "When comparing leprosy patients to HHC, 16 genes showed significantly different expression for leprosy patients (increased: FCGR1A, IL6, IL15, LRKK2, MBP, MSR1, PACRGv1, TLR1, TLR4; decreased: CAMTA, CD3E, CTLA4, CXCL13, GATA3, LAG3, TFGB)." (PMID 31784594, 2019). "A qPCR performed to evaluate pro- and anti-inflammatory related gene expression in skin lesions of leprosy patients revealed that pro-inflammatory genes STAT1, TNF, IFNG, IL15 and CSF2 are increased in PB cells, whereas anti-inflammatory MSR1 and PPARG genes are increased in MB cells." (PMID 34354699, 2021). "Infection of IL-15-derived MΦ, similar to MΦ in lesions from the self-limited form of leprosy, with M. leprae did not inhibit induction of the vitamin D antimicrobial pathway." (PMID 30300363, 2018). "In addition, intra-individual longitudinal analyses of leprosy patients before, during and after treatment of reversal reactions, indicated that several IFN-induced genes increased significantly at onset of reaction whereas IL15 decreased." (PMID 31784594, 2019).
Listeria infection (5 papers, 2013 to 2021). "The Vα3.2+ cells responded more strongly to IL-15, as well as showing bystander effector capability in a Listeria infection." (PMID 33897691, 2021). "Reconstitution of Il15ra-/- mice with Il15-/- bone marrow cells or vice versa conferred the ability to clear Listeria infection." (PMID 34956227, 2021). "It has been shown that DCs from C57BL/6 mice produce higher levels of IL-12 and IL-15 than DCs from BALB/c mice during early stages of Listeria monocytogenes infections." (PMID 29312229, 2017). "The findings of the present study substantiate this notion by demonstrating that IL-15 can elicit, independently of IL-15Rα, innate immune responses following Listeria infection that involve early IFNγ production necessary for pathogen control by sources other than NK cells." (PMID 34956227, 2021). "IL-15 expression in DCs is upregulated immediately after Listeria infection." (PMID 34956227, 2021). "In this work, we compared the requirement of IL-15 and IL-15Rα in controlling Listeria monocytogenes infection and determined that IL-15 signaling independent of IL-15Rα is critical for the induction of IFNγ and bacterial clearance." (PMID 34956227, 2021). "The source of IL-15 that confers protection against Listeria infection can be both hematopoietic and non-hematopoietic, as shown by the bone marrow radiation chimera experiments." (PMID 34956227, 2021). "Here, we compared the ability of mice lacking IL-15 (no signaling) or IL-15Rα (partial/distinct signaling) to control Listeria monocytogenes infection." (PMID 34956227, 2021). "Although IL-15 was required for uterine NK cell development and their recruitment to this site in the naïve state, a lack of IL-15 did not prevent the production of IFNγ early during Listeria infection." (PMID 25197644, 2014).
lymphocytic leukemia (5 papers, 2016 to 2023). "In another study, a transgenic mouse that overexpresses IL-15 by eliminating posttranscriptional checkpoints was used; NK cells and T cells increased robustly, causing fatal lymphocytic leukemia." (PMID 37585912, 2023). "In lymphoid leukemia, it has been described an increase of IL-15 and IL-5R." (PMID 28824651, 2017). "For example, transgenes comprising a non-cleavable, high-affinity CD16 and an interleukin-15 fusion protein has been used to augment the survival and function of FT596, the first ever iPSC-derived NK cells targeting CD19-positive lymphoid leukemias underwent a clinical trial (NCT04245722)." (PMID 38012684, 2023).
pancreatic ductal adenocarcinoma (5 papers, 2022 to 2024). An infiltrating adenocarcinoma that arises from the epithelial cells of the pancreas. "More recently, exercise was found to mobilize and accumulate tumor infiltration of IL15-responsive CD8+ T-cells in a murine model of pancreatic ductal adenocarcinoma, an effect that was also blocked with propranolol." (PMID 38592213, 2024). "Specifically, interleukin-15 (IL-15), acting as an upstream regulator, drives the proliferation and activation of IL-15Ra+ CD8+ T cells in pancreatic ductal adenocarcinoma." (PMID 38665847, 2024). "In addition, activation of IL-15 can be used as a promising therapeutic strategy for pancreatic ductal adenocarcinoma (PDA) and IL-15 is also one of the most promising prognostic markers for patients with biliary tract cancer (BTC)." (PMID 37251333, 2023).
periodontitis (5 papers, 2020 to 2024). An acute or chronic inflammatory process that affects the tissues that surround and support the teeth. "Despite the fact that the clinical presentation of periodontitis was similar among patients in groups 1, 2 and 3, it is noteworthy that WS IL-15 and -18 levels were nearly twice as high in groups -1 and -2 compared with Group-3." (PMID 36585711, 2022). "We previously demonstrated that nasal administration of periodontitis gene vaccine (pVAX1-HA2-fimA) or pVAX1-HA2-fimA plus IL-15 as adjuvant provoked protective immunity in the periodontal tissue of SD rats." (PMID 34399747, 2021). "Besides, we also compared the effect of CpG-ODN 1826 with that of the previously used IL-15 adjuvant to our pVAX1-HA2-fimA periodontitis gene vaccine in this study." (PMID 34399747, 2021). "IL-15 and IL-18 levels were higher in a group of non-smokers with periodontitis than in non-smokers without periodontitis." (PMID 39727461, 2024).
thyroid cancer (5 papers, 2021 to 2025). "In the thyroid cancer cell line FTC-133, the MMP3 and IL15 gene expressions were similarly regulated under RPM and spaceflight conditions." (PMID 40001606, 2025).